CD14 (CD14 molecule)
Diseases named in the same sentence as CD14 in open-access papers (continued):
Sharing a sentence is not in itself a finding about the gene and the disease.
breast cancer (continued). "In MBC patients receiving high-dose chemotherapy, high frequencies of mature CD14+HLA-DR+ monocytes, as well as specific subpopulations of CD8+ and CD4+ T lymphocytes, are associated with longer breast cancer-specific survival." (PMID 35626676, 2022). "Higher levels of T cells at early stages of differentiation have been detected in breast cancer patients (p < 0.05), and CD14+ myeloid cells from breast cancer patients have been shown to have enhanced ability to suppress autologous T-cell proliferation." (PMID 36035177, 2022). "Transfer of human CCR2-expressing CD14+ monocytes into CSF-1 supplemented nude mice with inoculation of human MDA-MB-231-derived metastatic breast cancer cells also led to selective tumor recruitment of CD14+ monocytes to lung." (PMID 34804061, 2021). "But overexpression of CD14 correlates with increased malignancy in breast cancer and colorectal cancer." (PMID 34335756, 2021). "According to multiple logistic regression analysis, the CD14+CD16++CD163+ subset was statistically significantly increased in patients with breast cancer." (PMID 35237501, 2021). "Several of the LXRE genes predicted increased regression-free survival in breast cancer subjects, among which Ptgs2, Mfge8, Anxa1, Spp1, S100a9 and Cd14 are biomarkers for MDSC and Treg cells." (PMID 33780491, 2021). "In order to examine the effect of the presence of breast carcinoma on the transcriptional programming of circulating monocytes, we compared the whole transcriptome of CD14+ monocytes from 9 patients with BC and 7 healthy female individuals by NGS (RNA-seq)." (PMID 35237501, 2021). "We were recently first to show that Mo-MDSCs (CD14+HLA-DRlow/−Co-receptorlow/− cells) are enriched in the peripheral blood of breast cancer patients." (PMID 31530882, 2019). "Accordingly, we performed whole exome sequencing (WES) of breast cancer patient-derived CD15+ PMN-MDSCs and CD14+ M-MDSCs to assess differences in ROS-associated mutation signatures." (PMID 31003475, 2019). "Herein, we have found a significantly higher number of CD14++/+CD16+ intermediate monocytes in patients with breast cancer." (PMID 30254632, 2018). "The percentages of macrophage-like cells in the peripheral blood, either in the PM-2 K+CD14+ (p = 0.0083) or the PM-2 K+CD14− subset (p < 0.0001), were significantly higher in patients with breast cancer than in healthy controls." (PMID 29614988, 2018). "The present results showed that the percentages of macrophages, in both the PM-2 K+CD14+ and PM-2 K+CD14− subsets, were significantly higher in patients with breast cancer than in healthy controls." (PMID 29614988, 2018). "This was in agreement with another study which has recently reported on the presence of elevated frequencies of CD14+HLA-DR−/low mMDSCs in early breast cancer." (PMID 30254632, 2018). "Metastatic human breast cancer samples compared to the indolent tumours also showed higher infiltration of CD14-positive (human mMDSC marker) cells." (PMID 28382931, 2017). "To provide evidence of mMDSC infiltration in human breast cancer samples, we performed immunohistochemical staining of 11 primary human tumour tissues with the CD14 antibody." (PMID 28382931, 2017). "Apart from MDA-MB-468, the TN breast cancer cells were also demonstrated to express the co-receptors CD14 and MD2 meaning that they harbor the necessary proteins for a functional TLR4 signal to occur." (PMID 26392082, 2015). "Herein, we report that serum soluble CD14 (sCD14) was revealed as the stable differential protein between LN+ER/PR-Her2+ (n=50) and LN-ER/PR+Her2- (n=50) breast cancer patients by proteomics analysis." (PMID 24086515, 2013). "It has been reported that in metastatic patients there was increased production of TNF-α and IL-1β compared with early breast cancer patients, and upregulation of CD14 and CD40, two receptors necessary for macrophage pro-inflammatory function and antigen presentation." (PMID 33804027, 2021).
breast cancer (continued). "We conclude that CD11c+FcεRI +CD14+CD1c+ iDCs infiltrating breast cancer align with DC3s." (PMID 32610077, 2020). "We established an in vitro model utilizing CD14+ cells isolated from healthy donors and CMs obtained from CAFs, NFs, and breast cancer cells in order to investigate the effects of the tumour stromal cells as well as the tumour cells on monocyte differentiation." (PMID 30816272, 2019). "However, the percentages of M2a- (p < 0.0001), M2b- (p < 0.0001), and M2c-like macrophages (p < 0.0001) in the PM-2 K+CD14+ cell population were significantly lower in patients with breast cancer than in healthy controls." (PMID 29614988, 2018). "The question of whether HER2 expression on CD14+ monocytes following trogocytosis is effective at providing an acquired immune response against HER2+ breast cancer cells is an important one." (PMID 25655677, 2015). "Notably, we found a significant enrichment of circulating Mo-MDSCs (CD14+HLA-DRlow/-Co-receptorlow/-) in patients with breast cancer." (PMID 25992611, 2015). "Other interesting candidates include CXCR4, a receptor implicated in mediating metastasis of breast cancer cells through its ligand SDF-1, and CD14 and lipopolysaccharide-binding protein (LBP), which are implicated in Toll-like receptor signaling and LPS-mediated inhibition." (PMID 20346151, 2010). "Interestingly, CD14+CD16+ monocytes have been proposed to be an early indicator of breast cancer." (PMID 30254632, 2018). "A considerable proportion of CD14 + CD16 + monocytes can be induced and expanded in breast cancer patients." (PMID 39955339, 2025). "The current study aimed to evaluate alterations in double-positive (CD14 + CD16 +) monocytes and sCD163 levels in response to NACT in an attempt to reveal their potential prognostic value in Egyptian breast cancer patients." (PMID 39955339, 2025). "We aimed to evaluate the potential therapeutic responses and possible predictive value of double-positive (CD14 + CD16 +) monocytes and soluble CD163 (sCD163) in Egyptian breast cancer patients." (PMID 39955339, 2025). "As for the CX3CR1 on CD14+ CD16- monocyte (p-value: 1.15×10−166), the IVW method clearly demonstrated a protective effect against ER- breast cancer." (PMID 38327747, 2024). "Specifically, M funiformis and Species Prevotellamassilia can affect breast cancer by CD38 on IgD+ CD24‐ and HLA DR on CD33br HLA DR+ CD14‐, respectively." (PMID 39654239, 2024). "Furthermore, studies have shown that CCL2 is highly expressed in tumor epithelial cells, and many CD14-positive cells are infiltrated in primary tumors, implying that high levels of CCL2 and CD14-positive cells can serve as diagnostic markers for early recurrence of breast cancer." (PMID 36403055, 2022). "Our own previous results on breast cancer (BC) patients revealed that the percentage of CD163-expressing CD14-CD16+ and CD14+CD16+ monocyte subpopulations was higher in BC patients compared to healthy women." (PMID 36733385, 2022). "Oestrogen deprivation of breast cancer cells increases migration of CD4+ T cells and decreases migration of CD11c+ and CD14+ PBMC towards cancer cells." (PMID 34602068, 2021). "It was demonstrated that CD163 is predominantly expressed on CD14+CD68+ monocyte-derived macrophages, which infiltrate tumor mass, indicating that NAC can induce the recruitment of CD163+ monocytes into breast cancer tumor." (PMID 35237501, 2021). "In breast cancer patients, both MDSC subsets (m-MDSC, CD14+ HLA-DR−; and g-MDSC, CD14− CD11b+ CD15+) appear to be more abundant than in healthy individuals." (PMID 33804027, 2021). "The inhibition of TLR2 or its downstream targets CD14, MyD88, and IRAK1 can inhibit the proliferation of human breast cancer (BRCA) cells." (PMID 33138076, 2020). "Since CD14 protein expression can be detected in a subset of BRCA1-null mouse tumor cells, as well as human breast cancers, further work will be necessary to validate its potential significance in human breast cancer." (PMID 32840210, 2020).
breast cancer (continued). "Human PBMCs were incubated with carboxyfluorescein succinimidyl ester (CFSE)-labeled SK-BR-3 breast cancer cells and after allowing time for ADCP to occur, cells were subsequently stained to mark monocytes (CD14) and evaluate viability (propidium iodide)." (PMID 31696314, 2019). "In the PM-2 K+CD14+ and PM-2 K+CD14− subsets, the percentages of M1-, M2a-, M2b-, and M2c-like macrophages were not significantly different between patients with HER2-positive breast cancer and those with HER2-negative breast cancer (c–j)." (PMID 29614988, 2018). "In the PM-2 K+CD14+ cell population, the percentage of M1-like macrophages that were CCR7+CD86+ was significantly lower in patients with breast cancer than in healthy controls (p < 0.0001)." (PMID 29614988, 2018). "It has also been shown that TAMs show high expression of CD14 and to some extent expression of HLA-DR and CD86 in breast cancer." (PMID 28750018, 2017). "Supporting the notion that HER2 trogocytosis is specific to HER2+ breast cancer, only low levels of HER2 expression were observed on the CD14+ and CD56+ cells of luminal type tumors (luminal type tumor)." (PMID 25655677, 2015). "A significant increase in HER2 expression on tumor-infiltrated CD14+ and CD56+ cells was observed after administration of the anti-HER2 antibody trastuzumab to HER2+ breast cancer patients." (PMID 25655677, 2015). "We initially performed a broad analysis on TLR and TLR2/4 co-receptor (CD14 and MD2) mRNA expression patterns in various breast cancer cell lines." (PMID 26392082, 2015). "Similar to the PBMCs of healthy volunteers, both the CD14+ and CD56+ immune effector cells in the PBMCs of breast cancer patients’ showed HER2-trogocytosis and target cell cytotoxicity." (PMID 25655677, 2015). "As highlighted in breast cancer, thymic stromal lymphopoietin (TSLP) plays a significant role in the tumor microenvironment, influencing the expansion of CD14+CD16+ monocytes, a subset of immune cells that are involved in inflammation and tissue repair, and modulating cellular metabolism." (PMID 40282539, 2025). "A recent study with breast cancer survivors showed that the number of intermediate (CD14+CD16+) and classical (CD14+CD16−) monocytes were increased after 45-min acute interval exercise but that the baseline resting levels of monocytes did not change after 16 weeks of chronic exercise training." (PMID 37085562, 2023). "We showed previously that MMTV-PyMT mammary tumors may originate from mammary alveolar LPs, which express TLR pathway genes (e.g., Tlr4, Cd14, Lbp)." (PMID 36765715, 2023). "Out study demonstrated that the main monocyte subsets (CD14+16-, CD14+16+, and CD14low16+) do not change in patients with breast cancer controlled by healthy individuals." (PMID 35237501, 2021). "The major transcriptional effects of DMHCA were linked to transrepression of a network of LXR-responsive genes, including PTGS2, S100A9, SPP1, CD14, CCL5 and ANXA1, which are overexpressed in MDSC and in a significant proportion of breast cancers, where they denote poor survival." (PMID 33780491, 2021). "In the PM-2 K+CD14+ and PM-2 K+CD14− subsets of macrophage-like cells, the percentages of M1-, M2a-, M2b-, and M2c-like macrophages were not significantly different between patients with HER2-positive and those with HER2-negative breast cancer." (PMID 29614988, 2018). "However, all monocyte subpopulations investigated (total CD14+-, classical CD14++CD16-, intermediate CD14++CD16+- and non-classical CD14+CD16++ monocytes) were largely unaltered across breast cancer groups (see S1A Fig for representative dot plots)." (PMID 25992611, 2015). "Similar to the CD14+ immune effector cells, the tumor-infiltrated CD56+ cells from HER2+ breast cancer patients expressed high levels of HER2 and the CD56+ cells from luminal type breast cancer patient showed little HER2 expression." (PMID 25655677, 2015).
breast cancer (continued). "As a negative control, we also tested HER2 expression on the CD14+ cells of a HER2− luminal type breast cancer patient; no HER2 expression was observed on the CD14+ cells of the luminal type breast cancer patient (luminal type tumor)." (PMID 25655677, 2015). "These were Estrogen Biosynthesis (HSD17B7 and HSD17B12), Estrogen-Dependent Breast Cancer Signaling (HSD17B7 and HSD17B12), Hepatic Fibrosis/Hepatic Stellate Activation (CD14 and CD40), Tight Junction Signaling (CDSF1 and OCLN), and Dopamine-DARPP32 Feedback in cAMP Signaling (CACNAID and CSNK1E)." (PMID 23759029, 2013). "Generating DCs from CD14+monocytes using GM-CSF, IL-4 and maturing them with TNF-α ± IFN-α (DCT and DCTI) is a novel strategy which was based on our previous work using monocytes from patients with operable breast cancer." (PMID 19298672, 2009). "The percentages of peripheral blood macrophages with neither (a) the PM-2 K+CD14+ expression profile nor (b) the PM-2 K+CD14− expression profile were significantly different between patients with HER2-positive breast cancer and those with HER2-negative breast cancer." (PMID 29614988, 2018). "Interestingly, it has been shown that in vitro exposure of human monocytes to CCL2 results in the enrichment of the CD14+CD16+ cell subset and that this chemokine is responsible for inflammatory monocyte accumulation induced by breast cancer cell microenvironment." (PMID 29312324, 2017). "Initially, our results confirmed the expression of TLR5 in a human monocyte line (THP-1) and isolated human CD14+ monocytes (Mo) using flow cytometry; in addition, the MDA-MB-231 breast cancer line was used as non-immune cell control." (PMID 36903639, 2023). "The results of the present study demonstrated that the percentages of macrophages in both the PM-2 K+CD14+ and PM-2 K+CD14− subsets were not different between patients with HER2-positive breast cancer and those with HER2-negative breast cancer." (PMID 29614988, 2018). "We confirmed low expression of HLA-DR and CD14, as well as negative expression of CD15 in breast cancer MDSCs." (PMID 29326716, 2017). "We found that in cells expressing both the TLR4 co-receptors MD2 and CD14 (MDA-MB-231 cells) TLR4-GFP was expressed in a vesicular pattern in the cytosol, whereas in breast cancer cells lacking both MD2 and CD14 (MCF-7 cells), TLR4-GFP was expressed evenly in the cytoplasm." (PMID 26392082, 2015). "Little or no HER2 expression was observed on the CD14+ and CD56+ PBMCs of the healthy volunteers and HER2− breast cancer patient; similarly, little or no HER2 expression was observed on the tumor-infiltrated CD14+ and CD56+ PBMCs of the HER2− breast cancer patient." (PMID 25655677, 2015). "Therefore, we analyzed the presence of CD14+HLA-DRlow/-Co-receptorlow/- (i.e. negative for co-receptors such as CD86 and CD80) Mo-MDSCs in the peripheral blood of breast cancer patients." (PMID 25992611, 2015). "However, the medians of CD14 and GPX3 in breast cancer patients did not have significant difference with the normal controls (p > 0.05)." (PMID 20346108, 2010).
viral infection (59 papers, 2009 to 2025). "On the other hand, mucosal NKp44+ ILCs18,21,22,68 and blood CD14+ cells are correlated with decreased risk of virus infection in both male and female macaques." (PMID 39438480, 2024). "The positive relationship between perinatal anxiety level and risk of RTIs in infants with the TT genotype of CD14 (rs2569190) might be due to the essential role of CD14 as an initiator of innate immunity against viral infections in the respiratory tract." (PMID 25263840, 2014). "In a viral infection, CD14+ cells also express other pattern recognition receptors that identify specific viral signals, such as their unique genetic material configuration." (PMID 38892107, 2024). "Most pathway enrichment was detected at day 7 post-infection, and, similarly to B-cells, genes related to viral infection sensing and initiation of an immune response against the infection were upregulated in CD14+ cells." (PMID 37920474, 2023). "This complexity in macrophage populations, in the context of viral infections, is highlighted by the observation that CD14+CD16+ cells also expressed CD206 and LYVE, which characterized TRM cells, as well as expressing CD183 and CX3CR1." (PMID 37485876, 2023). "We and others have previously shown that CD11b+CD33+CD14+HLA-DR-/lo monocytic MDSC (M-MDSC) are present in individuals with clinical recovery from viral infection." (PMID 35812392, 2022). "After infection, mCherry expression, indicating viral infection, remained restricted to CD14+ monocytes and resulted in a mean infection rate of ~15%." (PMID 35615366, 2022). "Soluble CD14 is studied as a marker for severe disease during viral infections, including in individuals with human immunodeficiency virus infection." (PMID 35429403, 2022). "With our data we support the notion on the involvement of CD14 in the generation of IFNs by human MΦs in response to a virus infection." (PMID 35203475, 2022). "In conclusion, our study provides further evidence in support of a contributory role of CD14 to sensing of viral infections besides its known high relevance for the recognition of bacterial components." (PMID 35203475, 2022). "High CD14+HLA-DRlo/neg MDSC frequencies have also been reported in other patients with viral infection, such as hepatitis B and hepatitis C." (PMID 33640878, 2021). "In SLE, type I interferon signaling pathway, defense response to virus and OAS activity were mainly enriched in CD14+ monocytes, similar to B cells, because virus infection and interferon pathway are closely related to the pathogenesis of SLE." (PMID 34079550, 2021). "Together, these results showed that in response to a viral infection, proportions of and the conserved host response to viral infection at a single-cell level in CD14+ monocytes increase with severity." (PMID 33765435, 2021). "The remaining 20 non-targetable SARS-CoV-associated disease genes include proteins (e.g., CD14, IFNA1, IFNB1, IL4, IL10, CCL5) having key roles in the immune-inflammatory response to viral infection as well." (PMID 33544720, 2021). "We found that the frequency of MDSCs decreased significantly 1 day after negative test results for SARS-CoV-2 compared to the frequency during active disease, suggesting that level of CD14+HLA-DRlo/neg MDSCs was related to viral infection." (PMID 33640878, 2021). "In contrast, all of the markers were expressed at high levels in the uninfected CD14-derived osteoclasts and further up-regulated by the viral infection in a dose-dependent manner." (PMID 25809599, 2015). "Because CD14 is dispensable for cytoplasmic sensing of viral infection, our data suggest that IFN-α production by pDC in the context of PBMC depends on a TLR mediated route." (PMID 24303065, 2013). "A significant alteration in response to viral infection was only observed for the CD14+ population, which was more diminished in the virus treated group as compared to the untreated group." (PMID 19125202, 2009).